IL6 (interleukin 6)
Diseases named in the same sentence as IL6 in open-access papers (continued):
Sharing a sentence is not in itself a finding about the gene and the disease.
Sepsis (continued). "Pro-inflammatory cytokines like IL-6, MCP-1, and IL-18 were elevated, as was the anti-inflammatory IL-10 in both sepsis cohorts compared to healthy controls." (PMID 40510342, 2025). "The primary outcomes assessed were levels of inflammatory markers such as IL-1β, IL-6, IL-8, IL-10, CRP, PCT, and TNF-α, providing a comprehensive overview of the effectiveness of the combined therapy on inflammatory responses in sepsis patients." (PMID 40667510, 2025). "We next focused on proinflammatory cytokines that play a major role in sepsis, including IFN-γ, TNFα, IL-6, and IL-1β." (PMID 40510337, 2025). "At early stage of sepsis, referred to as systemic hyperinflammatory response syndrome (SIRS), cytokines including tumor necrosis factor α (TNF‐α), interleukin (IL)‐1, IL‐2, IL‐6, are significantly elevated, which results in aberrant STAT3 activation." (PMID 41042728, 2025). "In the CLP-induced sepsis kidney injury model, the IL-2 gene exhibited low expression, whereas the CXCL8, IL-1β, TNF, IL-6, and IL-10 genes demonstrated high expression levels." (PMID 40166075, 2025). "In the early stage of sepsis, cytokines like tumor necrosis factor (TNF), interleukin-1β (IL-1β), and interleukin-6 (IL-6) mediate the inflammatory reaction, initiating the systemic inflammatory response syndrome (SIRS)." (PMID 40129981, 2025). "Numerous studies have shown low HDL-C but high TG in inflammatory and autoimmune diseases, including sepsis, IBD, systemic lupus erythematosus, and rheumatoid arthritis, and cytokines like TNFα, IL-1β, and IL-6 are thought to be involved." (PMID 40484317, 2025). "In sepsis-induced acute lung injury, upregulation of lncRNA H19 inhibited TNF-α, IL-1β, IL-6, IL-10, and BAX to suppress pulmonary apoptosis and inflammation." (PMID 39940682, 2025). "Sepsis-induced cholestasis, common in critical illness, is mediated by cytokines such as TNF-α, IL-1β, and IL-6, which disrupt bile transport, leading to intrahepatic cholestasis and raised conjugated bilirubin, ALP, and GGT." (PMID 40228343, 2025). "PN enhances bacterial clearance in sepsis by modulating adaptive immune responses, including suppression of TNF-α, IL-10, and IL-6 secretion, while concurrently reducing cellular apoptosis and increasing neutrophil counts." (PMID 40725434, 2025). "Neonates with EONS had higher levels of inflammatory and oxidative stress markers in UCB before the onset of symptoms; UCB IL-6, IL-10, and oxidative stress markers were significantly higher in infants with EONS, even in the proven sepsis group." (PMID 40171168, 2025). "Conditions such as sepsis, HLH, and CRS, especially in the context of chimeric antigen receptor (CAR) T-cell therapy, are typically characterized by markedly elevated IL-6 levels." (PMID 41155261, 2025). "We also assessed the relationship between circulating NETs and inflammatory biomarkers commonly used in sepsis management (e.g., CRP, PCT, and lactate), as well as emerging biomarkers such as IL-6 and MR-proADM." (PMID 41229414, 2025). "Compared with the control group, the sepsis group demonstrated significantly elevated values for body temperature, respiratory rate, neutrophil count, PCT, IL-6, and SOFA scores." (PMID 41567194, 2025). "IL-6 responds faster to infections than CRP and PCT, cementing its status as a key early indicator for sepsis." (PMID 41011807, 2025). "Pro-inflammatory cytokines, including IL-5, IL-6, and TNF-α released in sepsis, cross the blood–brain barrier and act on the hypothalamus and the pituitary to stimulate CRH and ACTH release, respectively." (PMID 39838305, 2025). "In addition, in a propensity score-matched analysis in 38 patients suffering from a cytokine storm caused by sepsis or severe trauma, CytoSorb therapy did not result in a significant reduction of plasma IL-6 concentrations compared with a matched control group." (PMID 40117010, 2025).
Sepsis (continued). "The five tested biomarkers, IL6, IL8, TREM-1, suPAR, and presepsin, have previously been shown to be remarkable biomarkers of sepsis with pneumonia (Larsen and Petersen 2017)." (PMID 39857101, 2025). "For example, IL-1β and IL-6 concentrations are higher in the hippocampus and serum of Sprague-Dawley male rats and C57BL/6 male mice with LPS-induced sepsis initiated during the dark compared to light phase." (PMID 39968295, 2025). "CSN6 upregulation increased IL-1β, IL-6, and TNF-α levels in an in vitro sepsis model (n = n = 6 per group)." (PMID 40595050, 2025). "In a CLP mouse model of sepsis, the system significantly reduced serum levels of inflammatory cytokines (TNF‐α, IL‐1β, and IL‐6), decreased mortality rates and protected against tissue damage." (PMID 40599085, 2025). "Macrophages drive the inflammatory response in the early stages of sepsis by releasing pro-inflammatory cytokines such as TNF-α and IL-6." (PMID 40124361, 2025). "In experimental models, genetic or pharmacological inhibition of CD38 attenuated pro-inflammatory cytokine production (e.g., IL-6, CXCL1), improved survival in cecal ligation and puncture (CLP)-induced sepsis, and mitigated multi-organ dysfunction." (PMID 41256846, 2025). "This is the first study to reveal significant IL-6 production in the renal stromal cells of mice with CD38-ligated sepsis and humans with severe sepsis." (PMID 39568061, 2025). "IL-6 and ferritin have been reported to rise acutely in CRS compared with sepsis, aiding differentiation." (PMID 41186785, 2025). "The values are presented as mean ± standard deviation for n = 9 animals in each group, at baseline (BL) and 8 h (*10 h for IL-6 and TNF) post-sepsis induction." (PMID 40993326, 2025). "The results showed that LPS injection significantly increased the levels of proinflammatory cytokines IL‐1β, IL‐6, and TNF‐α, confirming successful sepsis induction." (PMID 39836501, 2025). "IL-6 and CRP levels were concurrently elevated and significantly elevated during the initial phase of DKA with sepsis, followed by a significant decrease after DKA improvement." (PMID 39946377, 2025). "In sepsis, the JAK2/STAT3 pathway is specifically induced by IL-6, thereby initiating the proinflammatory effects of this cytokine through the generation of IL-6 trans-signaling." (PMID 39955435, 2025). "In contrast, the treatment group exhibited a statistically significant decrease in the expression levels of IL-6 (***P<0.001) and TNF-α (**P<0.01) compared to the sepsis group." (PMID 40822580, 2025). "Thus, utilizing IL-6 as an additional biomarker next to the granulocyte-to-lymphocyte ratio may enable more precise characterization of sepsis subentities, facilitating earlier diagnosis and tailored therapeutic interventions to prevent irreversible organ damage." (PMID 40178612, 2025). "Although biomarkers such as procalcitonin (PCT), interleukin-6 (IL-6), and C-reactive protein (CRP) have been extensively studied for the diagnosis of infection and sepsis, their clinical performance in immunosuppressed patients remains less clearly defined." (PMID 40428847, 2025). "In EBV-associated HLH, additional studies have shown disproportionately high IFN-γ and IL-10 with low IL-6, yielding IFN-γ/IL-6 and IL-10/IL-6 ratios that robustly differentiate EBV-HLH from sepsis." (PMID 41234904, 2025). "The present investigation aimed at assessing the prognostic performance of a multi-marker panel consisting of PT-INR, IL-6, and HDL cholesterol measured during admission in patients with severe sepsis." (PMID 40959673, 2025). "First, it provides a comprehensive analysis of multiple inflammatory markers, including CRP, IL-1β, IL-6, IL-8, IL-10, PCT, and TNF-α, which offers a detailed understanding of the immunomodulatory effects of ulinastatin in the treatment of sepsis." (PMID 40667510, 2025).
Sepsis (continued). "To confirm the anti-inflammatory activity of CBD in LPS-induced sepsis mouse model, we investigated the protein expression levels of inflammatory cytokines, such as TNF-α, IL-6, and IL-1β from the sepsis mouse serum samples." (PMID 41465451, 2025). "Mechanistically, IL-6 and ROS synergistically sustained the phosphorylation of STAT3 during early sepsis, thereby initiating the activation of the Shh pathway, by which the binding of Gli1 is potentiated to the Dio3 promoter." (PMID 39877839, 2025). "Consistent with this, all LPC species in our cohort were negatively correlated with IL-6, aligning with previous findings for LPC 16:0 in sepsis." (PMID 41007672, 2025). "The current biomarkers used for sepsis diagnosis, e.g., c-reactive protein (CRP), interleukin-6 (IL-6), and procalcitonin (PCT), have achieved partial success because most of these biomarkers are associated with inflammation and are not specific to infection." (PMID 40002629, 2025). "CRP: C-reactive protein; EOS: early-onset sepsis; FBC: full blood count; IL-6: interleukin-6; LOS: late-onset sepsis; PCT: procalcitonin; POC: point-of-care; VLBW: very low birth weight; WBC: white blood cell count." (PMID 40970024, 2025). "Elevated levels of potent cytokines, including IL-6, IL-1β, and TNF-α, are detectable in patients diagnosed with early-stage sepsis." (PMID 41256846, 2025). "In the initial hit phase, the sepsis-induced systemic inflammatory response syndrome (SIRS) triggers a significant release of pro-inflammatory cytokines, particularly TNF-α, IL-1β, and IL-6." (PMID 41451099, 2025). "Biomarkers such as CRP, PCT, IL-6, IL-8, CD64, and CD11b, are of great significance for early (24‒48 h) diagnosis of neonatal Sepsis and monitoring the effect of antibiotic treatment before bacterial culture detection results." (PMID 40774030, 2025). "In wild-type mice, levels of monocyte chemoattractant protein (MCP)-1, IL-1, IL-6, and TNF-α—elevated after sepsis induction—have been shown to decrease with cetirizine treatment." (PMID 41517447, 2025). "We subsequently sought to identify key pro-inflammatory mediators involved in sepsis, including TNF-α, IL-6, and the NLRP3 and RAGE signalling pathways." (PMID 41315622, 2025). "During sepsis, IL-10 is rapidly upregulated in response to pro-inflammatory cytokines such as TNF-α and IL-6." (PMID 41013722, 2025). "Subsequently, we measured the mRNA expression of SLC25A22, SLC25A33, and SLC25A37, along with that of pro-inflammatory cytokines, including TNF-α, IL-6, and IL-1β, in CD14+ monocytes from sepsis patients with liver abscesses." (PMID 40384854, 2025). "We therefore reasoned that sepsis lethality is determined by metabolic dysfunction and the ability to induce an APR in response to IL6." (PMID 39261648, 2024). "We focused on six cytokines that play a major role in sepsis: IFN-γ, IL-1β, IL-6, IL-10, IL-18 and TNF6." (PMID 38191855, 2024). "Twenty-four hours after sepsis induction, levels of the proinflammatory cytokines TNF-α, IL-6, and KC were significantly higher in the peritoneal lavage fluid of PLXNC1-/- mice, suggesting an inflammation-suppressing function for PLXNC1 in vivo during sepsis." (PMID 39169397, 2024). "EC ICAM‐1 expression, IL‐6 and soluble ICAM‐1 secretion increased significantly more after incubation with sepsis plasma compared with healthy plasma." (PMID 38981846, 2024). "The biomarker combination of IL-6 and CRP, measured at the time of sepsis suspicion, had the highest overall sensitivity (92%), but the lowest overall specificity (79%) in the subgroup analysis." (PMID 38671704, 2024). "The pathophysiology of sepsis is multifaceted, involving pro-inflammatory mediators such as tumor necrosis factor (TNF), interleukin-1 (IL-1), and interleukin-6 (IL-6), which are produced by the body in response to infection." (PMID 39205773, 2024). "IL-1β, IL-6, and TNF-α are all potent proinflammatory cytokines that contribute heavily to organ dysfunction from sepsis." (PMID 38646937, 2024).
Sepsis (continued). "Our study found that the level of serum IL-6 and TNF-α of sepsis mice was observed greatly upregulated at hyperinflammatory state and then dramatically downregulated at immunosuppressive state." (PMID 37776443, 2024). "Further correlation analysis revealed a close association between MASP-1 expression, the proportion of CD8 T cells, and IL6/JAK/STAT3 signaling scores in trauma and sepsis." (PMID 38384415, 2024). "In sepsis, monocytes show impaired functionality with a diminished capacity to release pro-inflammatory cytokines like tumor necrosis factor (TNF), IL-6, IL-12, and IL-1α." (PMID 38474403, 2024). "During sepsis, dysregulated release of inflammatory cytokines such as tumor necrosis factor-alpha (TNF-α), interleukin-1 beta (IL-1β), interleukin-6 (IL-6), and interleukin-10 (IL-10) can contribute to harmful effects." (PMID 39597952, 2024). "IL-6 exhibits a quicker response to infections than CRP and PCT, establishing its reputation as a prominent early biomarker for sepsis, notably in China." (PMID 39201697, 2024). "Our results showed that the anti-PD-L1 antibody markedly decreased the level of serum inflammatory cytokines interleukin (IL)-6, tumor necrosis factor (TNF)-α, and IL-10 in sepsis mice at 24 h, 48 h, and 72 h, respectively (P < 0.05)." (PMID 37776443, 2024). "On the other hand, during sepsis there is an acute release of multiple inflammatory mediators (TNF-α, IL-6, and IL-1β) which can lead to both tissue and organ damage, even contributing to cell death." (PMID 38474158, 2024). "Protection against severe sepsis was confirmed with the observation that TNF-α, IL-1β, IL-6, LDH, ALT and urea levels were decreased to almost basal levels in MFX-treated mice 24 h after CLP compared to untreated mice." (PMID 39200042, 2024). "Previous studies have also failed to observe an increase in leptin levels in inflammatory conditions such as sepsis, experimental endotoxemia, and HIV infection despite an elevation in IL-6 levels." (PMID 39200926, 2024). "IL-6 is widely used for assessing inflammatory activity, and AZU1 is a novel biomarker used for sepsis prognosis." (PMID 39407738, 2024). "IL-1β, IL-6, and TNF-α are common inflammatory factors that reflect the body’s inflammation levels, changing in response to infections, sepsis, or other inflammatory triggers." (PMID 39247187, 2024). "anshinol treatment in a rat sepsis model has been demonstrated to significantly increase AQP5 mRNA expression and reduce inflammatory cytokines IL-6 and TNF-α." (PMID 39544938, 2024). "Let-7b has been found to inhibit pro-inflammatory responses, especially IL-6 and TNF, by suppressing the TLR4/NFkB pathway in a mouse model of sepsis." (PMID 38400048, 2024). "Sepsis-induced inflammatory mediators, such as TNF-α, IL-6, and IL-1β, inhibited the protective anti-inflammatory cytokine IL-10." (PMID 38926458, 2024). "Our research showed that MT-ND6 and ANXA1 were more effective in the short-term prognosis of sepsis than commonly used laboratory markers like PCT, CRP, IL-6 and HBP." (PMID 39611143, 2024). "According to the study findings, GPS was able to reduce the inflammatory response in rats that had CLP-induced sepsis by reducing the TNF-, IL-1, and IL-6 levels in their BALF." (PMID 39268525, 2024). "Research has shown that LPS is a classical activator of AM, which binds to Toll-like receptor 4 to activate the NF-κB pathway, releasing pro-inflammatory mediators IL-6, TNF-α, etc., resulting in clinical manifestations of lung tissue injury and sepsis." (PMID 39355841, 2024). "It was reported that a high IL-6 level was observed both in children with cytokine release syndrome (CRS) after chimeric antigen receptor (CAR) T-cell therapy and in children with sepsis." (PMID 38672594, 2024). "To further confirm the prognostic role of PD-1+NK cells in sepsis, we compared the predictive performance between PD-1+NK cells and commonly used inflammatory markers, including CRP, PCT, IL-6, as well as SOFA score." (PMID 38953031, 2024).
Sepsis (continued). "We found that the levels of IL-6, TNF-α, and IL-10 in the serum were upregulated in CLP-induced sepsis mice than those in sham group." (PMID 37776443, 2024). "In our study, we observed a significant increase in NO levels and pro-inflammatory cytokines IL-1β, IL-6, and TNF-α in the serum of mice with CLP- and LPS-induced sepsis." (PMID 39337575, 2024). "The nomogram, which combines the TAPSE/PASP, IL-6, and LAC, demonstrated enhanced predictive efficacy for the prognosis of sepsis patients." (PMID 38961249, 2024). "The cytokine profile analysis revealed that ghrelin and Fer-1 effectively normalized the expression of IL-6, IL-1β, TNF-α, and IL-22, which were dysregulated during sepsis, highlighting their anti-inflammatory properties." (PMID 39857660, 2024). "Certain lncRNAs can modulate inflammatory variables including IL-6 and TNF-α, impacting the course of sepsis." (PMID 39735547, 2024). "Clinical studies have shown that intravenous Dex infusion reduces serum cytokine levels, including IL-1, IL-6, and TNF-α, as well as intra-abdominal pressure, to a greater extent than propofol infusion in patients with severe sepsis after abdominal surgery." (PMID 38419889, 2024). "There is convincing evidence linking high serum levels of inflammatory cytokines, such as IL-6, IL-1β and TNF-α, with hypophosphatemia in patients with sepsis." (PMID 38787228, 2024). "Suppression of IL-6 expression in plasma after GENT and (GENT and PTX) compared to PTX alone was observed among female and male pups, and compared to untreated sepsis only among female neonatal mice." (PMID 39963236, 2024). "The findings of our study are in agreement with the results of some others in this field, for example, it has been reported that in many inflammatory diseases such as sepsis, TNF-a, IL-1b and IL-6 serum levels increase significantly." (PMID 38952770, 2024). "This review will focus on IL-6, IL-1β, TNF-α, and IL-10 due to their well understood pathology in sepsis to further explore the shared pathophysiology of sepsis across both humans and horses." (PMID 39273060, 2024). "Regarding neutrophils, the levels of Tnfα, IL-6, IL-1β, CXCL1, CXCL2, CCL5, and CXCL10 increased significantly in response to sepsis sEVs compared with those from the control group and healthy individuals." (PMID 38910259, 2024). "HNF4α dysfunction also interferes with interleukin 6 (IL6)-induced, C/EBPβ and STAT3 controlled induction of APR genes and proteins, and hence interferes with liver regeneration in lethal sepsis." (PMID 39261648, 2024). "In the early stage of sepsis, monocytes/macrophages are rapidly recruited and release many inflammatory cytokines (e.g. IL-1β, IFN-γ, IL-6, TNF-α, and IL-10); subsequently, chemokines are released and acted on involved organs." (PMID 39320524, 2024). "These two cytokines are important pro-inflammatory cytokines in sepsis and high levels of IL-6 and TNF-α are correlated with increased disease severity and mortality during sepsis." (PMID 38562936, 2024). "The CLP-induced sepsis model was validated through overexpression of TNF-α, IL1-β, IL-6, and NF-kB, thereby demonstrating the occurrence of a systemic inflammatory response." (PMID 38629103, 2024). "Macrophages are essential to the pathophysiology of sepsis, as they secrete various pro-inflammatory factors such as TNF-α, IL-1, IL-6, and reactive nitrogen and oxygen species, which are crucial for fighting pathogens and tumors." (PMID 39337575, 2024). "Results showed that, as the sepsis severity increased, CD3+, CD4+, and CD4+/CD8+ levels decreased, while IL-6 and PCT levels rose significantly." (PMID 39201697, 2024). "As a corollary, in an acute infection a large IL-6 driven inflammatory response would lead to a strong suppression of HDL and is suggestive that low levels in sepsis is a bystander effect of high inflammatory reaction." (PMID 38290288, 2024).